MIR555 (microRNA 555)
Synonyms: hsa-mir-555; MIRN555
Gene: MicroRNA gene on chromosome 1 (155,346,350 to 155,346,445, reverse strand). Ensembl gene ENSG00000283701.
Homologues: Orthologues: chimpanzee ptr-mir-555 (100% identical).